CLDN1 (claudin 1)
Diseases named in the same sentence as CLDN1 in open-access papers (continued):
Sharing a sentence is not in itself a finding about the gene and the disease.
colorectal cancer (continued). "Our findings strongly suggest a central role of Prostaglandin E2-EP1 and EP2 receptor signaling to mediate AJC disassembly through a mechanism that involves PKC and claudin-1 as important target for the TJ-related effects in human colorectal cancer cells (Caco-2)." (PMID 19055708, 2008). "For example, the regulatory role of CLDN1 in chemoresistance has been proven for several malignancies, including colorectal cancer (CRC) and lung adenocarcinoma, thereby suggesting that CLDN1 expression in human malignancies may serve as a predictive marker of chemosensitivity." (PMID 40943068, 2025). "Some studies have suggested that it inhibits the translation of claudin-1, claudin-3, jam-1, and occludin in intestinal barrier tight junction proteins, reduce their stability, and lead to intestinal mechanical barrier dysfunction and promote the progression of colorectal cancer." (PMID 34820453, 2021). "Furthermore, the overexpression of CLDN-1 might be connected to MMP-9/Notch signaling to describe cellular proliferation in colorectal cancer." (PMID 33407452, 2021). "This underscores how the balance of different claudins (CLDN1 vs CLDN7) influences tumor behavior: CLDN1 up and CLDN7 down defines a particularly aggressive colorectal cancer phenotype." (PMID 40687428, 2025). "In colorectal cancer (CRC), CLDN1, CLDN2, CLDN4, and CLDN18 have been shown to either be upregulated or aberrantly expressed." (PMID 38540693, 2024). "Claudin 1 TJ protein has been recently reported to mediate RNA-binding protein LIN28B to promote invasion and liver metastasis of colorectal cancer." (PMID 37611445, 2023). "However, using the same functionalization strategy, our nanorods could be conjugated with different antibodies for different EV surface markers such as EpCAM, which is overexpressed in many types of cancers or claudin 1,7, and Cadherin-17, which are specific for colorectal cancer." (PMID 36514065, 2022). "Many claudins are dysregulated in a range of cancers, as in the case of the CLDN1 and CLDN2 genes, which are overexpressed in colorectal cancer." (PMID 35281827, 2022). "In tumors, OAS2 upregulates the expressions of E-cadherin, β-catenin, claudin-1, and snail, induces autophagy, and prolongs recurrence-free survival (RFS) in colorectal cancer." (PMID 36471952, 2022). "An internal fragment of tRNAArgCCG targets CLDN1 and inhibits epithelial to mesenchymal transition (EMT) of colorectal cancer cells." (PMID 35625858, 2022). "The blue line crosses the traditional threshold (horizontal line) and the TSA threshold (red line) indicating that the high expression level of claudin-1 was statistically significant with better OS and DFS of colorectal cancer." (PMID 32855635, 2020). "Here, we investigated the expression of claudin-1 (CLDN1), a major tight junction transmembrane protein, in the different colorectal cancer (CRC) molecular subtypes and then assessed the anti-tumor effect of a new anti-CLDN1 monoclonal antibody (mAb)." (PMID 28659146, 2017). "Primeaux V., with co-authors, demonstrated that CLDN1 regulates ephrin type-A receptor 2 (EPHA2), a tyrosine kinase, which activates the AKT signaling pathway and regulates CD44 expression in colorectal cancer (CRC) cells, thereby promoting the stemness of CRC and chemoresistance." (PMID 40943068, 2025). "However, the CLDN1 OE is shown to induce epithelial-to-mesenchymal metastasis, while CLDN7 acts as a tumor suppressor in colorectal cancer." (PMID 39175074, 2024). "From a clinical point of view, high CLDN2 in colorectal cancer appears to be linked to poor outcome in those receiving 5-FU treatment and CLDN1 and CLDN7 appear to form a claudin signature to predict the clinical response to chemotherapies in colorectal cancer." (PMID 38137355, 2023).
colorectal cancer (continued). "Our findings revealed that the mRNA expression levels of CLDN1, CLDN2, CLDN12, and CLDN14 were upregulated in colorectal cancer tissues relative to normal tissues in the Oncomine database, whereas CLDN3, CLDN5, CLDN7, CLDN8, CLDN11, CLDN15, and CLDN23 were downregulated, as previously reported." (PMID 35281827, 2022). "Previously, studies showed that in rat intestinal epithelium-derived line, IEC-6, caco-2 and colorectal carcinoma cells, downregulation of CDX2 by the MEK/ERK signaling pathway may decrease the protein expression levels of claudin-1, occludin and ZO-1." (PMID 30004434, 2018). "They confirmed, by immunoblotting, expression of claudin-1 to predominate in the nuclear and cytoplasmic fractions of SW480 cells (derived from primary colorectal cancer) and SW620 cells (derived from a metastatic lesion) as compared to RIE cells (derived from noncancerous rat intestinal cells)." (PMID 24868462, 2014).
hepatocellular carcinoma (56 papers, 2009 to 2025). A malignant tumor that arises from hepatocytes. "It was observed that blocking CLDN-1 with cCPE variants in the Huh7.5 hepatoma cell line inhibited infection of Huh7.5 cells with HCV in a dose-dependent manner and this also opened the epidermal barrier in the reconstructed human epidermis." (PMID 31952355, 2020). "In lung adenocarcinomas and hepatocellular carcinoma, enhanced invasiveness has also been demonstrated in association with claudin 1 loss." (PMID 26633531, 2015). "In hepatocellular cancer, down-regulation of CLDN1 was associated with poor differentiation." (PMID 30910845, 2019). "Therefore, we overexpressed wt or mutated forms of CLDN6 and OCLN in hepatoma Huh-7 cells that endogenously express CLDN1, -6 and OCLN proteins." (PMID 26561856, 2015). "As earlier reported, cell invasion and migration has been observed in normal liver and non-invasive human hepatocellular carcinoma due to overexpression of CLDN1." (PMID 39342193, 2024). "June-Hyungkim, while working on hepatoma cells, reported that lactate dehydrogenase B (LDHB) plays a compelling role in the process of invasiveness of hepatoma cells by activating the tight junction protein claudin-1 (Cln-1)." (PMID 36761981, 2023). "In hepatocellular carcinoma, the deletion of keratin 8 and keratin 18 promotes the proliferation, invasion, and metastasis of HepG2 cells by upregulating claudin 1 expression." (PMID 35789645, 2022). "CLDN1 is highly expressed in hepatocellular carcinoma and acts as a promoter of epithelial-to-mesenchymal transition (EMT) through the c-Abl-Ras-Raf-1-ERK1/2 signaling axis." (PMID 36620607, 2022). "Previous studies report that miR-29a regulates tumor growth and migration by targeting CLDN1 in hepatocellular carcinoma." (PMID 34838029, 2021). "It is reported that lactate dehydrogenase B (LDHB) suppression leads to hepatoma cell invasiveness via inducing CLDN1 expression." (PMID 35008557, 2021). "In contrast, the survival rate of patients with attenuated CLDN1 expression is lower than that with preserved CLDN1 expression, and lower CLDN1 induces the invasion of hepatocellular carcinoma." (PMID 32824620, 2020). "The substitution S305P/S307R/S313H improved cCPE binding to Cldn1 of Huh7 cells significantly compared to cCPEwt, providing a tool to target hepatoma cells potently." (PMID 31561440, 2019). "In summary, we showed that cCPE can be modified and used to prevent infection of hepatoma cells with HCV by binding to claudins including Cldn1, thus inhibiting formation of the viral entry complex." (PMID 31561440, 2019). "To elucidate the spatial interactions between TACSTD2 and CLDN1, we examined their localization in hepatoma cells by confocal microscopy." (PMID 29538454, 2018). "We and others have reported that claudin-1 associates with tetraspanin CD81; this receptor complex is present at the basolateral membrane of hepatoma cells and is essential for HCV entry in vitro." (PMID 23704991, 2013). "Some claudins also have been shown to have a prognostic role in particular tumor types, for example, claudin-3/-4 has a prognostic role in ovarian cancer, claudin-1 in colon cancer, claudin-10 in hepatocellular carcinoma and claudin-18 in gastric cancer." (PMID 23685873, 2013). "Immunoblot analysis of all four HCV entry factors (CLDN1, OCLN, SRBI, and CD81) in HFLC showed levels of expression comparable to those of the HCV-susceptible hepatoma Huh-7.5." (PMID 22144107, 2011). "Interestingly, downregulation of MRPL13 restrained the proliferation and migration of BC35, whereas it enhanced the invasiveness of hepatoma via the reactive oxygen species (ROS)-Claudin-1 pathway." (PMID 35739158, 2022). "Additionally, HCV infection altered TJ function with changes in localization of occludin and claudin-1 in hepatoma Huh7 cells, with occludin being required for HCV pseudotyped particles entry." (PMID 35328419, 2022).
hepatocellular carcinoma (continued). "Another study also reported an upregulation of claudin-1 expression in hepatoma cells by ROS." (PMID 36010553, 2022). "Recent studies have also provided evidence that Claudin-1 is aberrantly expressed in diverse types of human cancers including hepatocellular carcinomas (HCCs), and that Claudin-1 could induce EMT to enhance cell migration and invasion." (PMID 25830567, 2015). "Since primary human hepatocytes and the majority of human hepatoma cells express all four receptor proteins, and siRNA silencing approaches are frequently partial, it is difficult to study the role of claudin-1 in the HCV internalisation process in mammalian cells." (PMID 23704991, 2013). "This phenomenon is likely due to the role of claudins in tumor survival and invasion, as it is not unusual for some carcinomatous tissue to lose their TJ proteins as they grow and develop, for example, claudin-1 and -7 are typically downregulated in hepatocellular carcinomas." (PMID 23685873, 2013). "Similarly, Claudin 1 over-expression increased cell motility in oral squamous cell carcinoma, melanoma and hepatocellular carcinoma." (PMID 22675434, 2012). "In hepatocellular carcinoma (HCC), CLDN1 is not only highly upregulated at both the mRNA and protein levels compared to matched healthy adjacent tissue, but it also localizes at extra junctional locations in cancer cells." (PMID 38371623, 2024). "Further support for such speculations comes from studies that showed increased expression of claudin-1 induced expression of the EMT-regulating transcription factors such as ZEB1 in hepatocellular carcinomas, and claudin-1 can be exploited as a biomarker for liver cancer metastasis." (PMID 32309226, 2020). "However, in hepatoma cells, Cldn6 and Cldn9 appeared to function weaker than Cldn1." (PMID 31561440, 2019). "A recent work has showed the role of Claudin-1 as a promoter of the EMT via the c-Abl/Raf/Ras/ERK signaling pathway in hepatocellular carcinoma (HCC)." (PMID 24721839, 2014). "However, claudin-1 has been reported to associate with CD81 at the basolateral surface of polarized hepatoma cells, suggesting a role for non-junctional pools of claudin-1 in HCV entry." (PMID 22897233, 2012). "Also, CLDN1 expression in hepatocellular carcinoma (HCC) promotes the EMT via the c-Abl/Raf/Ras/ERK signaling pathway." (PMID 38731853, 2024). "In this paper, we evaluate the roles of three entry factors in polarized hepatoma spheroids: epidermal growth factor receptor (EGFR) and tight junction proteins claudin-1 (CLDN1) and occludin (OCLN)." (PMID 38157366, 2023). "In this study, we characterized the functions of the late host entry factors: epidermal growth factor receptor (EGFR), claudin-1 (CLDN1), and occludin (OCLN) during HCV entry into polarized hepatoma spheroids." (PMID 38157366, 2023). "In contrast, CLDN1 depletion increased the invasive and CSC-like properties of hepatocellular carcinoma cell lines." (PMID 36672179, 2023). "This was reminiscent of a previous study demonstrating that the corresponding peptide derived from claudin-1, named here CL1.1, inhibits HCV infection in hepatoma Huh7.5.1 cells." (PMID 36040168, 2022). "TJ protein, claudin-1, was first shown to be necessary for cell culture-replicating HCV entry into human hepatoma cell lines, as well as retroviral particles pseudotyped with HCV E1 and E2." (PMID 35328419, 2022). "Consistent with our data, CLDN1 suppressed E-cadherin and subsequently induced EMT in hepatocellular carcinoma cells." (PMID 34405008, 2021). "This protein is involved in the maintenance of the proper cellular localization of the two major HCV-entry cofactors, CLDN1 and OCLN, within hepatoma cells and primary human hepatocytes." (PMID 29538454, 2018). "In both parental and TACSTD2-overexpressing Huh7.5 cells, CLDN1 was co-immunoprecipitated by an anti-TACSTD2 antibody, indicating that the two proteins interact, either directly or indirectly, in hepatoma cells." (PMID 29538454, 2018).
hepatocellular carcinoma (continued). "To investigate the role of TACSTD2 in regulating CLDN1 and OCLN distribution in hepatoma cells, we performed TACSTD2 gene silencing using a pool of 4 siRNA (siTACSTD2) and examined the distribution of the two HCV-entry cofactors by confocal microscopy." (PMID 29538454, 2018). "In the present study, we documented that TACSTD2 is phosphorylated also in hepatoma cells and showed that the phosphorylated form of TACSTD2 interacts with CLDN1 and OCLN." (PMID 29538454, 2018). "Since TACSTD2 was reported to interact with the HCV-entry cofactor CLDN1 in human corneal epithelial cells, we examined the interaction between TACSTD2 and CLDN1 in hepatoma cells by co-immunoprecipitation." (PMID 29538454, 2018). "In hepatocellular carcinoma (HCC), overexpression of claudin-1 led to increased expression of transcription factors regulating epithelial-mesenchymal transition (EMT) of human liver cells." (PMID 27547510, 2016). "Forced expression of miR-198 in hepatoma cells inhibits the expression of the signal transducer genes c-MET and CDK4, which promote proliferative pathways, and increases the expression of E-cadherin and claudin-1, which maintain cellular adhesion." (PMID 41465470, 2025). "We screened GBVBpp infection of human hepatoma cell lines that were CRISPR/Cas9 engineered to ablate the expression of individual HCV receptors/entry factors and found that claudin-1 is essential for GBV-B infection, indicating the GBV-B and HCV share an entry factor." (PMID 37310242, 2023). "Later studies confirmed the role of claudin-1 in HCV entry and additionally found that claudins -6 and -9 also functioned well as cofactors for entry into CD81+ human endothelial cells but functioned poorly in hepatoma cells." (PMID 35328419, 2022). "The results of our gene silencing experiments demonstrated that TACSTD2 is involved in the maintenance of the proper cellular localization of two TJ proteins that are essential for HCV entry, CLDN1 and OCLN, both in hepatoma cells and in primary human hepatocytes." (PMID 29538454, 2018). "However, CLDN1 suppressed E-cadherin and subsequently induced EMT in hepatocellular carcinoma cells." (PMID 28867761, 2017). "As controls we included the well-characterized Huh-7 hepatoma line and the non-permissive claudin-1 null human embryonic kidney 293T cell line." (PMID 25701818, 2015). "According to our previous study and reports from others, anti-CLDN1 mAb and simeprevir exhibit no toxicity to hepatoma cells in vitro at the concentrations used in this study." (PMID 24830295, 2014). "Unexpectedly, we found that the presence of claudin-1 in proteoliposomes altered pseudoparticle uptake into hepatoma cells and that this modulation was not specific to HCV." (PMID 23704991, 2013). "In this regard, others have shown that human PBMC transcribe CLDN-6 but not CLDN-1 and that human hepatoma Bel7402 cell line was recognized by HCVpp despite that the cells did not express CLDN-1." (PMID 23626783, 2013). "The oligomeric pools of claudin-1 observed in yeast membranes were comparable with endogenous claudin-1 observed in Huh-7.5 hepatoma cells under non-reducing conditions." (PMID 23704991, 2013). "In regard to the TJ proteins, CLDN-1 protein was detected only in HCV-resistant PM1 T cells (∼30% of the signal displayed by Huh7.5 cells) and in HepG2 hepatoma cells (∼170% of the signal identified in Huh7.5), and at a lower level (∼25%) by control HEK-293 cells transfected with CD5." (PMID 23626783, 2013). "The exception seems to be the HCVpp permissive hepatoma cell line Bel7402, which is claudin-1 negative but expresses claudin-9." (PMID 19643019, 2009). "In addition, using hepatocellular carcinoma PDXs and lung cancer cases 1 and 2 PDXs, we established a system for simultaneously staining five membrane protein common cancer antigens EphB4, ROBO1, LAT1, CLDN1, GPC3, and HLA class I in six colors." (PMID 40076777, 2025).
hepatocellular carcinoma (continued). "Consistent with the observation that these cell lines already express the necessary levels of the four HCV entry factors, over-expression of CD81, SR-BI, CLDN1 or OCLN individually or in combination did not significantly increase HCVpp or HCVcc entry in any of the hepatoma cell lines." (PMID 22273112, 2012). "Furthermore the expression of claudin-6 and -9 in claudin-1 negative hepatoma cell lines was not effective in conferring the ability to become HCVpp permissive, but the expression of claudin-1 made the cell line permissive to HCVpp infection." (PMID 19643019, 2009). "The roles of tight junction proteins CLDN1 and OCLN had not been studied in the context of polarized hepatoma spheroids." (PMID 38157366, 2023). "Neither CAPN5 nor CBLB affected surface expression of SCARB1, CD81, CLDN1 and OLCN on human hepatoma cells." (PMID 30024968, 2018). "SR-B1 protein was found in T and hepatoma cell lines but not in PBMC or primary T lymphocytes, CLDN-1 in HCV-resistant PM1 T cell line and hepatoma cells only, while CLDN-6 equally in the cells investigated." (PMID 23626783, 2013).